BRCA2 (BRCA2 DNA repair associated)
Diseases named in the same sentence as BRCA2 in open-access papers (continued):
Sharing a sentence is not in itself a finding about the gene and the disease.
breast cancer (continued). "Germ-line mutations in the breast cancer genes BRCA1 and BRCA2 result in predisposition to breast and ovarian cancers (BRCA1) as well as other cancers (BRCA2)." (PMID 31890056, 2019). "Genetic testing that assesses the risk of breast cancer (BRCA1 and BRCA2) is currently only offered in university hospitals or highly specialized centers to help identify women with a family history of cancer who would benefit from early screening." (PMID 31155002, 2019). "Approximately 5–10% of breast cancers are hereditary and the vast majority of them are due to germline mutations in BRCA1 and BRCA2 tumor suppressor genes." (PMID 30621730, 2019). "Breast cancer risk for late onset cases (above 70 years old) who carry pathogenic mutation in BRCA1 and BRCA2 is 57 and 50%, respectively." (PMID 31477031, 2019). "According to the National Comprehensive Cancer Network guidelines and the Japanese Breast Cancer Society guidelines, annual MRI should be performed as part of regular check-ups for individuals with BRCA1 or BRCA2 mutations." (PMID 30980249, 2019). "Around 5–10% of all breast cancers are attributed to somatic or germline mutations in the genes BRCA1 and BRCA2." (PMID 31092228, 2019). "This is essential if a patient is considered to be at higher than average risk (i.e., having a strong family history of breast cancer or personal history of breast cancer, benign breast disease, or inherited BRCA1 and/or BRCA2 mutations)." (PMID 31354818, 2019). "Her sister, my aunt, was diagnosed with breast cancer at 27 and was dead by 33 she tested positive for BRCA2 as well." (PMID 31199327, 2019). "HR defects occur in between 25 and 40% of breast cancers, from both germline and somatic mutations of key components of the HR pathway such as BRCA1/BRCA2." (PMID 31320901, 2019). "Although PVs in several genes have been associated with an increased risk of breast cancer, two genes BRCA1 and BRCA2, appear to account for more cases of hereditary breast (and ovarian) cancer than the others." (PMID 30832243, 2019). "In this age group there is a higher proportion of patients with pathogenic variants in genes that predispose to breast cancer, such as BRCA1 or BRCA2, compared with patients who have onset of breast cancer at an older age." (PMID 31491032, 2019). "Eleven women with a positive family history previously underwent surgery for breast cancers, and in five cases BRCA1 (n = 4) or BRCA2 (n = 1), pathogenic alterations were detected in the ovary tumor samples." (PMID 31653094, 2019). "In current practice for breast cancer prediction, there is a focus on presenting risk of breast cancer over time and/or likelihood of being a carrier of a BRCA1 or BRCA2 pathogenic variant (PV)." (PMID 30832243, 2019). "High penetrance breast cancer susceptibility genes — BRCA1 and BRCA2 are responsible only for 5–10% of familial breast cancers." (PMID 31312277, 2019). "A decreased expression of BRCA2 was detected in high-methylated BRCA2 breast cancer samples and vice versa." (PMID 31506496, 2019). "In breast cancer, germ line mutations in BRCA1 and BRCA2 are examples of genomic instability that increases tumor susceptibility." (PMID 29478325, 2019). "Among the 35 (24%) BRCA-mutated breast cancer patients, 22 and 13 harbored deleterious BRCA1 or BRCA2 mutations, respectively." (PMID 31355134, 2019). "The main risk factor for familial breast cancer is the presence of mutations in BRCA1 and BRCA2 genes." (PMID 31341521, 2019).
breast cancer (continued). "Two paternal cousins were suffering from early onset breast cancer and the youngest resulted positive to BRCA2 genetic screening." (PMID 31336956, 2019). "From these data, short‐term hematologic toxicities during breast cancer chemotherapy appear similar which should be reassuring for clinicians administering, and patients with a BRCA1 or BRCA2 mutation receiving, chemotherapy." (PMID 31407530, 2019). "Therefore, it is conceivable that genomic instability mediated by deficiency in BRCA1 and BRCA2 may give rise to immunophenotype in breast cancer predictive of response to immunotherapy such as increased expression of PD-L1 and PD-1 and higher abundance of tumour-infiltrating immune cells." (PMID 31022191, 2019). "Most breast cancer cases are sporadic; however, approximately 5% of breast cancers are attributable to germline BRCA1 or BRCA2 mutations." (PMID 31454914, 2019). "Although the pathological features of BRCA1 breast cancer and BRCA2 breast cancer reported in our study were similar to that of Western studies, the rate of triple-negative breast cancer was very high (89%) in the BRCA1 L63X mutation group." (PMID 31143373, 2019). "Taken together, our results suggest that PALB2-associated breast cancers with bi-allelic inactivation are similar to breast cancers with BRCA1 and BRCA2− bi-allelic inactivation in terms of genetic instability and genomic features indicative of HRD." (PMID 31428676, 2019). "Family history of breast cancer, inherited BRCA1 and/or BRCA2 mutations, alcohol intake, and exogenous hormone intake are known risk factors underlying the elevated incidence rate of breast cancer." (PMID 31817161, 2019). "Lifetime risk to develop breast cancer and ovarian cancer is enhanced up to 85% and up to 54% respectively in the carriers of BRCA1 and BRCA2 mutations." (PMID 31608277, 2019). "The cumulative risk of breast cancer by age 80 years was estimated to 72% for BRCA1 carriers and 69% for BRCA2 carriers." (PMID 31060517, 2019). "This quality improvement study and cost-effectiveness analysis evaluates mainstream genetic testing using cancer-based criteria to determine eligibility for BRCA1 and BRCA2 testing in patients with breast cancer." (PMID 31125106, 2019). "The age at breast cancer onset was 40.3 years, 40.4 years, and 41.6 years in the BRCA1 L63X mutation-positive group, other BRCA1 mutation-positive group, and BRCA2 mutation-positive group, respectively." (PMID 31143373, 2019). "Breast Cancer 1 (BRCA1) located on chromosome 17 and Breast Cancer 2 (BRCA2) located on chromosome 13 are tumor-suppressor genes involved in the DNA double-strand breaks (DBS) repair mechanisms." (PMID 31405066, 2019). "The primary screen focused on 74 genes previously shown to be synthetic lethal with olaparib in BRCA1 and BRCA2-proficient MCF7 breast cancer cells." (PMID 30889383, 2019). "In one study of Korean women with breast carcinoma histories in their families, the BRCA mutation prevalence was 21.7% (BRCA1 = 9.3% and BRCA2 = 12.4%)." (PMID 30713775, 2019). "In high genetic risk breast carcinoma patients, the BRCA1 and BRCA2 germline mutations were identified by applying next-generation sequencing." (PMID 30713775, 2019).
breast cancer (continued). "In the British population, in patients with breast carcinomas who are younger than 36 years old, the BRCA1/2 mutation prevalence was 5.9% (BRCA1 = 3.5% and BRCA2 = 2.4%)." (PMID 30713775, 2019). "In the French population, in breast carcinoma patients who are younger than 46 years old, the BRCA1/2 mutation prevalence was 9.1% (BRCA1 = 6.5% and BRCA2 = 2.6%)." (PMID 30713775, 2019). "Prophylactic contralateral mastectomy has been shown to reduce the risk of death from breast cancer in BRCA1 and BRCA2 carriers by approximately 50%." (PMID 29266833, 2018). "Estimated cumulative breast cancer risk by age of 70 conferred by pathogenic variants in BRCA1 and BRCA2 is approximately 60 and 50%, respectively." (PMID 30410870, 2018). "Hereditary breast cancer is well-described; around 5–10% of breast cancer patients carry high risk gene mutations like BRCA1 and BRCA2." (PMID 29409476, 2018). "We received data from 84 Chinese breast cancer patients who had known pathogenic BRCA1/2 mutations, which included 63 different types of mutations (22 BRCA1 and 41 BRCA2)." (PMID 29487695, 2018). "Unfortunately, access to magnetic resonance imaging screening only became available for BRCA1 or BRCA2 carriers and women with a medical history of breast cancer half way through the study." (PMID 29318406, 2018). "The mean age at breast cancer diagnosis was 40.1 years for BRCA1 and 44.4 years for BRCA2 mutation carriers." (PMID 29937543, 2018). "In this regard, it is notable that the only confirmed modifier of breast cancer risk, RAD51:c.135G > C, modifies risk only in BRCA2 pathogenic mutation carriers." (PMID 29422015, 2018). "BRCA1 and BRCA2 are widely recognized as caretaker genes for the genome and tumor suppressor genes for breast cancer." (PMID 29321957, 2018). "This study confirmed that patients diagnosed with invasive breast cancer aged 18–40 years have a high breast-cancer-specific mortality, and a high proportion are BRCA1 and BRCA2 mutation carriers." (PMID 29337092, 2018). "In one study, mutations in ten different genes associated with breast cancer were evaluated in CMT (by iPLEX genotyping of sixty-three single nucleotide polymorphisms), but only BRCA1 and BRCA2 were significantly associated with the development of this tumor." (PMID 30373614, 2018). "We undertook the Prospective Outcomes in Sporadic versus Hereditary breast cancer (POSH) study, the primary aim of which was to determine the effect of inherited BRCA1 or BRCA2 mutations on outcomes in patients with young-onset breast cancer." (PMID 29337092, 2018). "Founder mutations in the two breast cancer genes, BRCA1 and BRCA2, have been described in many populations, among these are Ashkenazi-Jewish, Polish, Norwegian and Icelandic." (PMID 29339979, 2018). "Patients in the immediate reconstruction group significantly more often had a genetic predisposition to breast cancer (i.e., BRCA1, BRCA2, and/or CHEK2 mutations; p < 0.001) and a lumpectomy in their medical history (p = 0.032)." (PMID 29399731, 2018). "Mutations in breast cancer susceptibility gene type 1 and type 2 (BRCA1 and BRCA2) put women at a higher risk of developing breast and/or ovarian cancer." (PMID 29459887, 2018). "Breast cancer and ovarian cancer are hormone driven and are known to have some predisposition genes in common such as the two well known cancer genes BRCA1 and BRCA2." (PMID 29671401, 2018). "The present study demonstrates a clear protective effect of early first pregnancy on breast cancer risk in both BRCA1 and BRCA2 mutation carriers." (PMID 29116468, 2018). "Most of the articles focused on the risk of developing ovarian and breast cancer, by examining the presence of BRCA1 and BRCA2 mutations." (PMID 30619456, 2018).
breast cancer (continued). "The absolute risk of breast cancer by the age of 80 years is 75% and 76% for protein truncating mutations of BRCA1 and BRCA2, respectively, far higher than any other mutation associated with hereditary breast cancer." (PMID 30174725, 2018). "A meta-analysis of available studies in Asian women revealed pooled estimates of breast cancer risk by age 70 of 44.8% (95% CI 33-57.2%) and 40.7% (95% CI 31.3-50.9%) for BRCA1 and BRCA2 mutation carriers respectively." (PMID 29861850, 2018). "Patients having two or more first-degree relatives with ovarian cancer usually have an early onset of the disease, especially with the breast cancer gene 1 and 2 (BRCA1 and BRCA2) germline mutations or Lynch syndrome." (PMID 30050740, 2018). "We offered genetic testing of BRCA1 and BRCA2 to > 800 patients with newly diagnosed breast cancer and provided written pre-test information instead of in-person pre-test genetic counseling." (PMID 29164420, 2018). "Between 5 and 7% of the breast cancer cases are due to hereditary factors, and 25% of these are down to genetic mutations in BRCA1 and BRCA2 genes." (PMID 30061853, 2018). "To test the search engine’s ability to accurately match variants from full-text disease queries, we first searched “early-onset breast cancer,” returning the expected alleles in BRCA1 and BRCA2 (4335 variants, 0.037 ± 0.020 s)." (PMID 29409527, 2018). "Approximately 70% of breast cancers arising in BRCA1 mutation carriers and up to 23% of breast cancers in BRCA2 carriers are triple-negative." (PMID 29514593, 2018). "The family history characteristics of the carriers did not stand out with the exception of a stronger family history for male breast cancer, reported in second degree relatives of three BRCA2 E13908X carriers." (PMID 30400234, 2018). "About 5–10% of breast cancers are linked to inherited gene mutations (BRCA-1 and BRCA-2 mutations are the most common), while about 85% of cases occur in women who have no family history of breast cancer." (PMID 30441769, 2018). "Breast cancer risk for BRCA1 and BRCA2 pathogenic mutation carriers is modified by risk factors that cluster in families, including genetic modifiers of risk." (PMID 29422015, 2018). "PIN1 knockdown significantly reduced LYN Y397 phosphorylation in a human BRCA2 mutant breast cancer cell line and in primary mouse Brca2 null tumor cells." (PMID 30590041, 2018). "Among the 15 patients with bilateral or second primary breast cancer; 10 (66.7%) had deleterious or suspected deleterious BRCA1/2 mutations; 5 (33.3%) were in BRCA2 and 5 (33.3) in BRCA1." (PMID 29409476, 2018). "Women with germline BRCA1 or BRCA2 mutations are recommended to undergo prophylactic bilateral salpingo-oophorectomy (RRSO) to reduce their risk of developing ovarian cancer (and breast cancer), usually by age 40 or after the completion of childbearing." (PMID 29389895, 2018). "Female BRCA1 and BRCA2 carriers from North West England were assessed for breast cancer incidence prior to 50 years of age comparing those with an early first full-term pregnancy (< 21 years) to those without a full-term pregnancy." (PMID 29116468, 2018). "The Bahamas has the highest known prevalence of BRCA mutations among breast cancer patients of any country; 23% of women with breast cancer in the Bahamas were found to carry one of seven founder mutations in the BRCA1 or BRCA2 gene." (PMID 29266833, 2018). "In general, Hong Kong has the highest estimated risk of breast cancer by age 70 years for both BRCA1 and BRCA2 carriers, but still much lower than that in Caucasians (40-87% for BRCA1 and 27-84% for BRCA2)." (PMID 29861850, 2018).
breast cancer (continued). "Despite its genetic wealth, few breast cancer genetic studies have been performed in the TUN population such as those that focused on the identification of the mutational spectrum of BRCA1 and BRCA2." (PMID 30594178, 2018). "Our previous results showed that less than 10% of the clinically high risk breast cancer patients harbor BRCA1 and BRCA2 mutations, and importantly, nearly half of the mutations were recurrent mutations." (PMID 29487695, 2018). "About 5–10% of all breast cancer (BC) cases are due to inherited predisposition, and about 20–40% of these cases are caused by germline mutations in BRCA1 and BRCA2 genes." (PMID 29884136, 2018). "The two missense variants BRCA2:c.91T >G (p.Trp31Gly) and PALB2:c.3262C >T (p.Pro1088Ser) were detected in two breast cancer probands originally ascertained at Breast Cancer Units of Institutes located in Milan and Bergamo (Northern Italy), respectively." (PMID 30410870, 2018). "Women carrying a pathogenic variant (PV) in the BRCA1 or BRCA2 (BRCA1/2) genes are at high lifetime risk of developing breast cancer (BC) and ovarian cancer (OC), but estimation of the cumulative risk of cancer to age 70 years varies substantially between studies and populations." (PMID 30430080, 2018). "Data from the Breast Cancer Linkage Consortium suggest the risk of epithelial ovarian cancer through age 70 years is up to 44% in BRCA1 families and is up to 27% in BRCA2 families." (PMID 29389895, 2018). "It has been described that MERIT40 cooperates with BRCA2 (breast cancer 2) to resolve DNA interstrand cross-links." (PMID 30065170, 2018). "Cumulative cancer risks at age 70 years were breast cancer risk of 57% for BRCA1 and 49% for BRCA2 mutation carriers; and ovarian cancer risk of 40% for BRCA1 and 18% for BRCA2 mutation carriers." (PMID 30263092, 2018). "For BRCA2 carriers, the corresponding risks were 55% for breast cancer, 16.5% for ovarian cancer, and 62% for contralateral breast cancer." (PMID 29409476, 2018). "Mutations in ATM, BRCA2, and PALB2 were also more frequent in patients with PC with a family history of breast cancer (first- or second-degree relative)." (PMID 31497750, 2018). "In total, 938 of 2514 women (37.3%) were diagnosed with breast cancer, 630/1550 BRCA1 (40.7%) and 308/964 BRCA2 mutation carriers (32.0%)." (PMID 29937543, 2018). "The few studies on genetic susceptibility for breast cancer in the Sri Lankan population have focused mainly on the BRCA1 and BRCA2 genes." (PMID 29433565, 2018).